CXCR4 (C-X-C motif chemokine receptor 4)
Diseases named in the same sentence as CXCR4 in open-access papers (continued):
Sharing a sentence is not in itself a finding about the gene and the disease.
breast carcinoma (continued). "Examination of breast cancer studies in the Oncomine database supports the possibility that CXCR4 can regulate MMP12 expression: MMP12 expression correlated significantly with CXCR4 expression, and not with CXCR7 expression." (PMID 22152016, 2011). "Using CA9 as a surrogate marker of hypoxia, we demonstrated that hypoxia is associated with the accumulation of Treg and also the subset of CXCR4 positive Treg in breast cancer." (PMID 21521526, 2011). "Clinicopathological features of 69 patients with primary breast carcinomas and methylation status of CXCR4 gene." (PMID 22220212, 2011). "These epidemiological data corroborate in vitro experiments that have demonstrated that CXCR4-tropic virus interact with breast cancer cells and induce their apoptosis." (PMID 21443771, 2011). "The chemokine receptor CXCR4 is highly expressed by breast cancer cells and is involved in metastasis formation." (PMID 21443771, 2011). "Concordantly, an elevated migratory signaling response to ectopic CXCL12 was also shown to contribute to the metastatic potential of CXCR4-expressing mammary carcinoma cells, subsequent to epigenetic silencing of autocrine CXCL12." (PMID 21349176, 2011). "Another downstream component of the Ras signaling pathway, NF-κB, promotes breast cancer cell migration and thus metastasis by inducing chemokine receptor CXCR4." (PMID 21609483, 2011). "Chemokine receptor CXCR4 is a seven membrane spanning G-protein coupled receptor and has been shown to be overexpressed on various malignant cancers including breast cancer." (PMID 21915267, 2011). "It has been shown that in a xenograft mouse model that the down-regulation of CXCR4 leads to the suppression of mammary tumor growth." (PMID 21785640, 2011). "The effect of hMSC on proliferation and migration of MCF-7 cells was decreased to baseline control levels when both the ER and CXCR4 were inhibited, suggesting the involvement of ER-CXCR4 crosstalk in breast cancer progression." (PMID 21087507, 2010). "CXCR4 surface expression was significantly increased in the two human breast cancer cell lines, MDA-MB-231 and MCF7, following exposure to hypoxia." (PMID 20492653, 2010). "The observed 28% prevalence of CXCR4-using HIV in our control group and 90% lower risk of breast cancer associated with these HIV strains, would account for most of the breast cancer deficit in women with AIDS." (PMID 21179547, 2010). "Due to evidence of ER-CXCR4 crosstalk involvement in breast cancer progression, we examined the effects of simultaneous inhibition of ER and CXCR4 signalling to decrease hMSCs influence on MCF-7 cells." (PMID 21087507, 2010). "We propose that one of the mechanisms underlying this increased metastatic ability and poorer prognosis is that tumour hypoxia through upregulation of CXCR4 cell surface expression leads to increased metastatic potential of breast cancer cells." (PMID 20492653, 2010). "These investigators found that high levels of SDF1α are produced in many organs and tissues commonly affected by metastatic breast cancer, while CXCR4 appears to be expressed in human breast cancer cells and metastatic lesions." (PMID 20492653, 2010). "The knockdown of CXCR4 expression by a small interfering RNA in breast carcinoma cells decreases cell invasion and proliferation in vitro and abrogates the tumor growth in vivo." (PMID 20569497, 2010). "It has been demonstrated that downregulation of CXCR4 inhibits in vitro invasiveness of breast cancer cell and blocks breast cancer metastasis in vivo." (PMID 21167057, 2010). "Our data extend these findings by demonstrating that blockade of CXCR4 inhibits both spontaneous and experimental metastasis in a more biologically relevant orthotopic model of breast cancer." (PMID 20849618, 2010). "Through interaction with its cognate ligand, the chemokine stromal-derived factor-1 (SDF-1/CXCL12), CXCR4 is proposed to direct homing of breast cancer cells to particular sites of metastases." (PMID 21167057, 2010).
breast carcinoma (continued). "Our data support these findings showing that breast cancer cells are sensitive to the microenvironment, in particular oxygen levels which can lead to upregulation of CXCR4 cell surface expression." (PMID 20492653, 2010). "Several studies have reported the inhibition of metastasis of human MDA-MB-231 breast cancer cells in SCID mice using anti-CXCR4 antibodies, siRNA or peptide antagonists of CXCR4." (PMID 20849618, 2010). "CXCR4 signalling in response to SDF1α was found to induce chemotaxis and migration of breast cancer cells." (PMID 20492653, 2010). "Recent studies have revealed that the chemokine receptor CXCR4 also plays a critical role in the regulation of breast cancer cell invasion and metastasis." (PMID 21167057, 2010). "They found that high levels of SDF1α are produced in many organs and tissues commonly affected by metastatic breast cancer, while CXCR4 appears to be expressed in human breast cancer cells and metastatic lesions." (PMID 20492653, 2010). "Reflecting our previous studies in breast cancer carcinomas, CXCR4 surface expression was unaltered between control and CXCL12-expressing cells." (PMID 20877573, 2010). "Other studies have demonstrated that CXCL12 transactivates HER2 in breast cancer cells, enhancing the expression of CXCR4 and favouring metastases." (PMID 20946648, 2010). "Recently, it has been demonstrated that the overexpression of HER2/neu in breast cancer enhances the metastatic potential through the upregulation of CXCR4, providing a link between CXCR4 and HER2/neu in tumor progression and metastasis." (PMID 20049170, 2010). "According to previous studies, invasion of CXCR4-expressing breast cancer cells is enhanced in response to SDF-1/CXCL12." (PMID 21167057, 2010). "Hypoxia and Hif-1a have been shown to upregulate CXCR4 in carcinomas such as lung cancer, oral squamous cell carcinoma, breast carcinoma, and renal cell carcinoma." (PMID 20102637, 2010). "Malignant breast cancer cells express CXCR4, invade the extracellular matrix, and circulate in the blood and lymphatic vessels attracted by CXCL12 that is abundantly released by target metastatic organs." (PMID 20049170, 2010). "Only 2 (9%) breast cancer cases had CXCR4-tropic HIV, compared to 19 (28%) of the matched controls (Fisher's exact P = 0.09)." (PMID 21179547, 2010). "In summary, CXCR4-SDF1α receptor-ligand axis plays an important role in the metastatic ability of breast cancer cells." (PMID 20492653, 2010). "Two (9%) of 23 breast cancer cases had CXCR4-tropic HIV, compared to 19 (28%) of 69 matched controls." (PMID 21179547, 2010). "In agreement with the data reported by Cos and colleagues, we have demonstrated that melatonin, at physiological concentrations (10-9 M), significantly inhibits the invasion of MCF-7/6, MCF-7/Her2.1, and MCF-7/CXCR4 breast cancer cells." (PMID 21167057, 2010). "More than twenty types of cancer (for example breast cancer, ovarian cancer, glioma, pancreatic cancer, prostate cancer, cervical cancer, colon carcinoma, and renal cancer) overexpress CXCR4." (PMID 27713313, 2010). "In a mouse model of breast cancer, neutralizing antibodies to CXCR4 significantly limited metastases to lymph nodes and lung." (PMID 20492653, 2010). "Muller and colleagues first observed that CXCR4 is commonly and often highly expressed in primary breast cancers and in breast cancer cell lines." (PMID 21179547, 2010). "Out of all the known chemokine receptors, breast cancer cells specifically express active CXCR4 and CCR7, the ligands of which are HCXCL12 and CCL21, respectively." (PMID 20181250, 2010). "Muller demonstrated that CXCR4 is consistently expressed in human breast cancer cells, malignant breast tumor and metastasis tumors, while its ligand CXCL12 is preferentially expressed in the lungs, liver, bone marrow, and lymph nodes." (PMID 20181250, 2010).
breast carcinoma (continued). "As a result, we have considered and minimized competing risk as much as possible and still found a significant association between CXCR4-tropic HIV and reduced risk of breast cancer." (PMID 21179547, 2010). "The ability of wild-type CXCL12 to inhibit both primary tumor growth and metastasis makes it a more attractive candidate than the CXCR4 antagonist for incorporation into therapeutic strategies for breast cancer." (PMID 20849618, 2010). "CXCR4 is more highly expressed in human breast cancer metastases to bone than to the lungs or brain." (PMID 19727403, 2009). "Müller and colleagues provided initial evidence linking CXCL12/CXCR4 biological axis to breast cancer metastasis to specific organs, which was confirmed in non-small lung cancer." (PMID 19563666, 2009). "Autocrine VEGF regulates the expression of the chemokine receptor CXCR4, which mediates the migration of breast carcinoma cells toward CXCL-12, required for tumor cells invasion but not for their survival." (PMID 19226458, 2009). "In this study, we examined the relationship of Nrp2 to lymph node metastasis, VEGF-C expression, and CXCR4 expression in human breast cancer tissues, and further investigated the potential value or relevance of Nrp2 for predicting disease outcome." (PMID 19580679, 2009). "Using our microfluidic endothelium, we confirmed that CXCR4 or CXCR7 on breast cancer cells promotes intravascular adhesion throughout the channel, supporting a mechanism through which these receptors expressed on cancer cells promote metastasis." (PMID 19484126, 2009). "The activation of a paracrine loop CXCR4/CXCL-12 involving tumor cells and stromal fibroblasts induces tumor growth in implants of MCF-7 breast carcinoma cells with cancer associated fibroblasts (CAF)." (PMID 19226458, 2009). "Previous studies showed that treatment with CXCR4 antagonists inhibited breast cancer metastasis to bone and lung and decreased bone destruction due to myeloma bone metastases in mice, which supports our results." (PMID 19727403, 2009). "Nrp2 expression is significantly correlated with VEGF-C expression, cytoplasmic CXCR4 expression, and lymph node metastasis in breast cancer." (PMID 19580679, 2009). "Previous reports demonstrated that up-regulated CXCR4 expression in human cancers, including breast cancer, was correlated with lymph node metastasis and unfavorable prognosis, and was regulated by nitric oxide." (PMID 19580679, 2009). "PICP induces the expression of Metalloproteinases-2 and -9, of Vascular endothelial growth factor and of the chemokine CXCL-12 receptor CXCR4 in MDA MB231 breast carcinoma cells in vitro." (PMID 19226458, 2009). "Inaddition to mediating the directional homing of primary breast cancer cells tosecondary organ sites, CXCR4 and CXCL12 are important in other aspects ofcancer progression, such as adhesion, proliferation, and angiogenesis." (PMID 19325924, 2009). "Previous studies also demonstrated that up-regulated CXCR4 expression in human breast cancer is correlated with lymph node metastasis and unfavorable prognosis." (PMID 19025611, 2008). "This suggests that small molecule CXCR4 antagonists, such as T140 analogs, can replace anti-CXCR4 antibodies as neutralizers of metastasis of breast cancer." (PMID 19787093, 2008). "Recent evidence suggests that metastatic breast cancer cells overexpress CXCR4 and that this receptor plays a critical role in homing of cancer cells at specific metastatic sites." (PMID 19025611, 2008). "Metastasis of breast cancer cells to the lung in mice was inhibited by neutralizing CXCR4 with anti-CXCR4 antibodies." (PMID 19787093, 2008). "Chemokine receptor CXCR4 is involved only in some partially clarified steps of carcinoma (breast, prostate) metastatic process, and silencing CXCR4 blocks breast cancer metastasis." (PMID 18941460, 2008).
breast carcinoma (continued). "When indicated, the chemoattractant CXCL12 was added in the bottom chamber to induce CXCR4-positive breast cancer cell to invade through the Matrigel (specific chemoinvasion)." (PMID 18941460, 2008). "As CXCR7 expression also promotes cancer metastasis in breast cancer, it would be important to investigate the correlation between CXCR4 and CXCR7 in breast cancer in future studies." (PMID 19025611, 2008). "T140 analogs inhibited in dose-dependent manners the migration of a CXCR4-positive human breast carcinoma cell line MDA-MB-231 induced by CXCL12." (PMID 19787093, 2008). "CXCR4 expression is therefore a generalmarker for the spread of breast cancer to its secondary sites, and for aggressivestages of the disease." (PMID 18779872, 2008). "First, UMB-2 was tested on a variety of formalin-fixed, paraffin-embedded human breast cancers, which have previously been reported to express CXCR4." (PMID 19116653, 2008). "In this study, immunohistochemistry revealed that cytoplasmic CXCR4 expression was significantly correlated with nitrotyrosine levels, lymph node metastasis, and distant organ metastasis in human breast cancer." (PMID 19025611, 2008). "We then showed that incubation of MDA-MB-231 and SK-BR-3 breast cancer cells with an NO donor results in induction of cytoplasmic CXCR4 expression." (PMID 19025611, 2008). "CXCL12 was reported to activate the migration of human melanoma and breast cancer cells that express CXCR4, ROBO1 and ROBO2, while SLIT2-ROBO interaction was demonstrated to inhibit chemotaxis, chemoinvasion and adhesion of breast cancer cells." (PMID 19114000, 2008). "Individual CXCR4-expressing tumor cells have beenfound in the peripheral blood of breast cancer patients, and CXCR4expression in breast cancer has been associated with the presence of individualtumor cells in the bone marrow of patients." (PMID 18779872, 2008). "In vivo studies have confirmed the importance of CXCL12/CXCR4 interactions in breast cancer metastasis." (PMID 17726466, 2007). "These oligosaccharides also significantly inhibited CXCL12-induced migration of CXCR4-expressing LMD MDA-MB 231 breast cancer cells." (PMID 17726466, 2007). "The inhibitory potential of TN14003 a CXCR4 peptide antagonist has been previously studied in inhibiting breast cancer metastasis and inhibiting the migratory and invasive ability of human pancreatic cancer cell lines." (PMID 18001467, 2007). "More specifically, recent evidence suggests that the CXCR4/CXCL12 axis plays an integral role in guiding metastatic cells from breast carcinoma." (PMID 17261188, 2007). "The only known receptor for CXCL12, CXCR4, was previously shown to be expressed in different cancers including cutaneous melanoma, colon cancer, prostate cancer, breast cancer and neuroblastoma." (PMID 17261188, 2007). "Expression of the chemokine receptor CXCR4 allows breast cancer cells to migrate towards specific metastatic target sites which constitutively express CXCL12." (PMID 17726466, 2007). "Although the interaction of CXCR4 with the lymphatic system has not been investigated as intense as the hematogeneous dissemination, CXCR4 inhibition resulted in suppression of breast cancer lymph node metastases, implying common routes in both systems." (PMID 17176471, 2006). "Müller and colleagues provided initial evidence linking the CXCL12/CXCR4 biological axis to breast cancer metastasis to specific organs, which was confirmed in non-small cell lung cancer." (PMID 17083723, 2006). "The role of CXCL12/CXCR4 axis in organ-specific metastasis was initially suggested in breast cancer." (PMID 17083723, 2006). "Muller and coworkers found CXCR4 to be highly expressed in breast cancer cells, malignant breast tumours and metastases." (PMID 15987445, 2005). "NF-κB, in turn, regulates the motility of breast cancer cells by directly up-regulating the expression of CXCR4." (PMID 15978137, 2005).
breast carcinoma (continued). "CXCR4 was, however, even more highly expressed in normal bone marrow and normal lung, two breast cancer metastasis sites, than in the breast tumours studied." (PMID 16189523, 2005). "The CXCR4 promoter consistently (with the exception of patient 2) achieved the highest luciferase activity in the breast cancer tissue slices." (PMID 16457694, 2005). "CXCR4, identified as a co-receptor for HIV-1, is a chemokine receptor recently implicated in the metastatic homing of breast cancer cells to alternative tissues." (PMID 16457694, 2005). "In contrast, CXCR4 mRNA expression was detected in all eight breast cancer cell lines, in MRC5 and HECV cells, and in breast cancer tissue (data not shown)." (PMID 15987445, 2005). "As demonstrated in our study, the CXCR4 promoter showed the highest level of expression and specificity for breast cancer tissue, corroborating the evidence in the literature for a clear link to breast cancer pathobiology." (PMID 16457694, 2005). "Again, in most of the tumor samples, the CXCR4 promoter displayed the highest luciferase activity, consistent with the results obtained in breast cancer cell lines." (PMID 16457694, 2005). "Recently CXCR4 has been shown to be expressed by tumor cells in breast cancer, non-small cell lung cancer, pancreatic cancer, prostate cancer, thyroid cancer and to play an important role in their metastatic process." (PMID 15978137, 2005). "It has been reported that CXCR4 gene expression is markedly up-regulated in breast cancer cells, but is undetectable in normal mammary primary epithelial and stromal cells." (PMID 16457694, 2005). "The CXCR4 gene plays a major role in progression and metastasis of various tumor types and is, therefore, a rational target for breast cancer therapy." (PMID 16457694, 2005). "Muller and coworkers found that SDF-1/CXCR4 plays a critical role in determining the metastatic destination of breast cancer cells." (PMID 15987445, 2005). "The organ-specific spread of breast cancer cells to different sites, including the lymph nodes, has been reported in a mouse model to require the chemokine receptor CXCR4 on tumour cells and the chemokine CXCL12 in target organs." (PMID 16189523, 2005). "Using real-time PCR, we found CXCR4 expression to be significantly higher in breast carcinoma cells than in normal mammary tissue, in concordance with others." (PMID 16189523, 2005). "Overall, the CXCR4 promoter exhibited the highest luciferase activity in breast cancer cell lines, primary breast cancer cells and breast cancer tissue slices." (PMID 16457694, 2005). "Chemokine receptor CXCR4 was found to be involved in HIV infection and was highly expressed in human malignant breast tumors and the ligand for CXCR4, CXCL12 (SDF-1), exhibited high expression in organs in which breast cancer metastases are often found." (PMID 15978137, 2005). "In a recent publication, CXCR4 was shown to be highly expressed in breast cancer cells, malignant breast tumours as well as metastases." (PMID 11953881, 2002). "Therefore, our study provided significant insights into the expression patterns of TGFβ1 and CXCR4 and their involvement with other proteins, for instance VCAN, and WNT whose role is known in causing breast cancer stemness and hence cancer aggressiveness." (PMID 41348904, 2025). "Furthermore, soluble factors secreted by breast cancer cells can stimulate NFs to express CXCR4 and transdifferentiate into CAFs, promoting the transport of macrophages to tumor sites." (PMID 40890855, 2025). "In a cancer setting, maintaining subsets of activated receptors at the plasma membrane would result in signal potentiation that increases invasiveness and subsequent metastasis, for example, in CXCR4-mediated cell motility, growth, and tumorigenesis in breast cancer cells." (PMID 41100251, 2025).